POSTN (periostin)
Diseases named in the same sentence as POSTN in open-access papers (continued):
Sharing a sentence is not in itself a finding about the gene and the disease.
cardiomyopathy (8 papers, 2011 to 2024). A disease of the heart muscle or myocardium proper. "This blockade strategy offers promising therapeutic targeting in dystrophin-deficient cardiomyopathy as, in cardiac fibroblasts, AngII was further found to increase periostin expression via Ras/p38 MAPK/CREB and ERK1/2/Tgf-β1 pathways." (PMID 38255321, 2024). "The strong periostin overexpression we observed together with the risk described for developing cardiomyopathy in ALMS patients is particularly suggestive of a role of periostin in cardiac remodeling in ALMS." (PMID 21541333, 2011). "Importantly, the analysis of receiver-operating characteristic (ROC) curve revealed that the changes in serum periostin levels might serve as a possible biomarker for cardiomyopathy in diabetic patients." (PMID 37993768, 2023). "As above, it is undeniable that POSTN could be a potential biomarker or target for cardiomyopathy." (PMID 35282347, 2022). "Several of the proteins impacted by myectomy (POSTN, MMP12, CDON, NAMPT, HAMP, LTA4H) were previously reported to be altered in cardiovascular disease, cardiomyopathy, or vascular disease with effects mediated through inflammatory mechanisms." (PMID 33804404, 2021). "In addition, ferroptosis-related genes could provide us with a novel direction of exploration in HCM and DCM, respectively, and 3 hub genes (POSTN, IGFBP5, and FMOD) could be potential biomarkers or therapeutic targets in cardiomyopathies." (PMID 35282347, 2022).
coronary artery disease (8 papers, 2014 to 2025). "Nevertheless, these findings suggest a potential for exosomal short-length periostin in ischemic heart disease; however, further studies are needed to optimize the therapeutic benefit." (PMID 33897872, 2021). "Periostin was proved to be related closely to the onset and development of coronary artery disease." (PMID 24586384, 2014).
esophageal cancer (8 papers, 2013 to 2025). A primary or metastatic malignant neoplasm involving the esophagus. "These include SPP1 (osteopontin), SPARC, and POSTN (periostin), all of which have been implicated in esophageal cancer progression." (PMID 40872572, 2025). "Relationship between circ‐POSTN expression and clinicopathological features of esophageal cancer patients." (PMID 38553795, 2024). "Upregulation of periostin has been observed in a wide variety of cancers including colon, gastric, and esophageal cancer." (PMID 34283070, 2021). "The secretion of periostin by CAFs triggers paracrine signaling through which CAF-derived periostin acts as a ligand to bind to integrins expressed on the surface of esophageal cancer cells." (PMID 31137693, 2019). "This has also been described in the pancreatic parenchyma, in which periostin creates a tumor-supportive niche by sustaining fibrogenic stellate cell activity, and in esophageal cancer, in which periostin facilitates tumor invasion." (PMID 24146092, 2014). "Indeed, targeting the periostin–integrin axis has been suggested as a strategy to impede tumor–stromal cooperation in esophageal cancer." (PMID 40872572, 2025). "In Esophageal Cancer COL3A1 is overexpressed with POSTN which further emphasizes the joint role they could have with CTHRC1." (PMID 36190948, 2022). "Nevertheless, the biological functions of circRNA periostin (circ‐POSTN) in esophageal cancer (EC) progression and radiosensitivity have not been well elucidated." (PMID 38553795, 2024).
hypertensive nephropathy (8 papers, 2012 to 2022). Kidney damage that results from chronically elevated blood pressure; complications include glomerular damage resulting in proteinuria and hematuria. "In the kidney, periostin has been implicated in progression of hypertensive nephropathy and it was increased in glomeruli of patients with progressive proteinuric disease." (PMID 31726998, 2019). "Together, the results of this work identify periostin as a previously unrecognized marker associated with hypertensive nephropathy." (PMID 22403621, 2012). "And in an animal model experiment of hypertensive nephropathy, periostin is involved in the progression of kidney injury and reflects its progression." (PMID 33241962, 2020). "For example, periostin was found to be produced by vascular cells in hypertensive nephropathy, by tubular epithelial cells in ureteral obstruction and PKD, and by glomerular podocytes and parietal epithelial cells in glomerulonephritis." (PMID 28536691, 2017). "Accordingly, using the model of L-NAME-induced hypertensive nephropathy, we identified periostin as one of the most highly expressed genes in a transcriptomic analysis." (PMID 28536691, 2017). "Periostin levels in renal tissue and urine were significantly higher among diabetic rats and patients with glomerulopathies, hypertensive nephropathy and CAN." (PMID 25884625, 2015). "To evaluate the importance of periostin as a marker and/or an actor of kidney disease progression, we performed regression analyses with hallmarks of hypertensive nephropathy severity as dependent variables." (PMID 22403621, 2012). "Our results identified a progressive induction of periostin in the kidney with the progression of the hypertensive nephropathy." (PMID 22403621, 2012). "Periostin is a 93.3-kD secreted cell adhesion protein, which has been shown to be a critical regulator of bone metabolism, hypertensive nephropathy, and wound repair." (PMID 23056395, 2012). "Hypertensive nephropathy was characterized by a strong increase in periostin staining in the media and the adventitia of renal vessels." (PMID 22403621, 2012). "We concluded that periostin expression more than indices of endothelial or tubular dysfunction was strongly related to the progression and the regression of experimental hypertensive nephropathy, independently of changes in systolic blood pressure." (PMID 22403621, 2012). "Interestingly, the analysis of histological fibrosis scores shows that the difference between Reg and No Reg groups was most evident for perivascular fibrosis, in accordance with periostin distribution in experimental hypertensive nephropathy." (PMID 22403621, 2012). "Furthermore, independent of blood pressure, periostin was strongly correlated with plasma creatinine, proteinuria and renal blood flow, hallmarks of hypertensive renal disease severity." (PMID 22403621, 2012).
Insulin resistance (8 papers, 2016 to 2025). Increased resistance towards insulin, that is, diminished effectiveness of insulin in reducing blood glucose levels. "Plasma periostin levels were strongly associated with plasma TG, chronic inflammation, and insulin resistance." (PMID 27313402, 2016). "Elevated circulating periostin level was associated with an increased risk of having NAFLD and insulin resistance among overweight and obese individuals." (PMID 27885258, 2016). "Certainly, further experiments are required to elucidate the interaction of periostin and insulin resistance." (PMID 27885258, 2016). "In conclusion, the present study found that plasma periostin levels were significantly higher in T2DM and obese subjects and were strongly associated with TG metabolism, chronic inflammation, and insulin resistance." (PMID 27313402, 2016). "We observed a significant positive correlation between circulating periostin levels and fasting plasma insulin, and insulin resistance assessed by HOMA-IR in overweight and obese individuals, but not in normal weight participants." (PMID 27885258, 2016). "In addition, MMP9, TIMP1, SPP1 and POSTN were shown to play a role in regulating fat metabolism and insulin resistance." (PMID 35966072, 2022). "Besides, DEX-induced hyperglycemia, hyperinsulinemia and insulin resistance were also partially reversed by Periostin antibody." (PMID 31918919, 2020). "In agreement, both administration of a Periostin-neutralizing antibody and genetic ablation of Periostin largely attenuated DEX-induced hepatic steatosis, hyperglycemia and insulin resistance, indicating that Periostin plays an important role in the GCs-induced metabolic side effects." (PMID 31918919, 2020). "Moreover, increased circulating periostin levels were also significantly correlated with increased insulin resistance, particularly among overweight and obese subjects." (PMID 27885258, 2016).
muscular dystrophy (8 papers, 2021 to 2024). Muscular dystrophy (MD) refers to a group of more than 30 genetic diseases characterized by progressive weakness and degeneration of the skeletal muscles that control movement. "Periostin (Postn) encodes a matricellular protein also produced by activated cardiac fibroblasts, the activity of which is linked to fibrosis in muscular dystrophy." (PMID 39268580, 2024). "Other ECM-related genes, POSTN (Periostin) and COL6A2 (Collagen, type VI, alpha), are also appealing candidates as they have been directly linked to myogenesis and muscular dystrophy, respectively." (PMID 38413582, 2024). "Altogether, we provide further evidence of the involvement of periostin in fibrotic pathology in skeletal muscle using a model of muscular dystrophy." (PMID 38255321, 2024). "This coincides with the upregulation in periostin, confirming its potential as a fibrotic marker for this muscular dystrophy." (PMID 38255321, 2024). "It is noteworthy that periostin upregulation has been previously documented in other murine models of muscular dystrophy, when contrasted against their wildtype counterparts." (PMID 38255321, 2024). "Immunoblotting clearly verified the increased concentration of specific isoforms of annexin, periostin and collagen in muscular dystrophy." (PMID 36362832, 2022). "Understanding the contribution of the various Periostin isoforms to skeletal muscle fibrosis could highlight new therapeutic targets or biomarkers for this aspect of muscular dystrophy phenotypes." (PMID 38892298, 2024). "Understanding the contribution of periostin to skeletal muscle injury and fibrosis holds substantial potential in unveiling novel avenues for therapeutic intervention and disease biomarker identification within the context of the muscular dystrophy phenotype." (PMID 38255321, 2024). "The contribution of Periostin to this process is supported by the finding that increased expression of Periostin in the δ-sarcoglycan-null mouse model of muscular dystrophy exacerbates disease pathology, while its deletion has a positive effect on the reduction of fibrosis." (PMID 38892298, 2024). "Finally, several ECM proteins change their expression in muscular dystrophies, including periostin, tenascin-c, TSP-1, and TSP-4." (PMID 35177651, 2022).
psoriasis (8 papers, 2022 to 2025). An autoimmune condition characterized by red, well-delineated plaques with silvery scales that are usually on the extensor surfaces and scalp. "Among the downregulated proteins identified in our analysis, periostin stands out as a marker with a possible relation to a clinical improvement in psoriasis, although more research is warranted to examine this further." (PMID 39201477, 2024). "We noted that periostin was the most downregulated protein in our analysis, with a 37% lower level in plasma from patients with psoriasis." (PMID 39201477, 2024). "On the other end of the spectrum, periostin was the most downregulated protein in sera from patients with psoriasis." (PMID 39201477, 2024). "In our study, we analyzed the involvement of periostin (POSTN) in the pathogenesis of psoriasis, as one of the extracellular matrix proteins belonging to the fasciclin family." (PMID 38003486, 2023). "Not just limited to the liver, the synergistic effect of TNFα and IL-17 on periostin expression has also been noted in other inflammatory diseases, such as psoriasis, in which it leads to altered keratinocyte differentiation." (PMID 35056404, 2022). "Periostin has been reported to be highly abundant in AD skin, contributing to itch, but is strongly reduced in psoriasis." (PMID 35805110, 2022). "Here we show that serum and basal keratinocyte periostin expression is elevated in psoriasis." (PMID 37773198, 2023). "POSTN deposits were localized in the epidermis in 66% of patients with psoriasis." (PMID 38003486, 2023). "Since previous animal studies have shown that periostin promotes arterial calcification and its deletion protects against atherosclerosis, the increased serum periostin could play a role in the systemic inflammation described in psoriasis patients." (PMID 37773198, 2023). "The role of POSTN in the pathogenesis of psoriasis remains unclear." (PMID 38003486, 2023). "The ROC curves demonstrated that the expression levels of eight Hub Genes—POSTN, CD274, CD24, SERPINB3, CXCL13, SMPD3, BIRC5, and RAB27A—exhibited high accuracy (AUC > 0.9) in classifying the Psoriasis and Control groups." (PMID 40557155, 2025).
squamous cell carcinoma (8 papers, 2013 to 2023). A carcinoma arising from squamous epithelial cells. "Periostin is also involved in the invasion and metastasis of some cancers, including squamous cell carcinoma." (PMID 36598904, 2023). "Interestingly, inhibition of EGFR signaling was also shown to attenuate POSTN-mediated cell migration and invasion in esopahageal squamous cell carcinoma supporting a relationship between POSTN and EGFR pathway." (PMID 29946533, 2018). "Interestingly, periostin level is significantly higher in squamous cell carcinoma than in adenocarcinoma, and slightly higher in male than in female although not statistically, which is opposite to ceruloplasmin." (PMID 28088789, 2017). "The aim of the study is to determine the cytoplasmic expression of POSTN in NSCLC as well as in some histological subtypes such as adenocarcinoma (AC) and squamous cell carcinoma (SCC) in relation to clinicopathological data and prognosis." (PMID 35163164, 2022). "In addition, the expression and function of POSTN in stromal cells (CAFs) in NSCLC have not been sufficiently studied, especially in respect to two distinctive histological groups, i.e., squamous cell cancer (SCC) and adenocarcinoma (AC)." (PMID 32987711, 2020).
thyroid cancer (8 papers, 2007 to 2024). "Periostin is a mesenchyme-specific protein that, when overexpressed, is associated with aggressive forms of thyroid cancer." (PMID 35626065, 2022). "By analyzing microarray data from the GEPIA database, we also found that POSTN levels were positively correlated with STAT3 and IL-4 is strongly linked to STAT6 in thyroid cancer." (PMID 38773979, 2024). "To investigate the role of POSTN in thyroid cancer, we first determined the expression of POSTN in clinical samples." (PMID 38773979, 2024). "Taken together, our results indicate that POSTN is significantly increased in papillary thyroid tumors and correlates with poor prognosis of patients with thyroid cancer." (PMID 38773979, 2024). "Timer 2.0 database analysis showed that the expression level of POSTN was positively correlated with CAF infiltration in thyroid cancer." (PMID 38773979, 2024). "For example, stromal SOD3 had a stimulatory effect on thyroid cancer cell growth and an inhibitory effect on cancer cell migration, POSTN expression was activated by ΔNp73 and modulated epithelial-mesenchymal transition of thyroid cancer cells." (PMID 36973751, 2023). "Our analysis concludes that TIMP1, LOX, CD276, IFNA1, TLR2, and POSTN are identified as thyroid cancer biomarkers, which lead to the different clinical courses of a woman older than 55 years old with papillary thyroid cancer." (PMID 36120433, 2022). "Especially CD276, POSTN, and IFNA1 may be considered as new biomarkers associated with the prognosis of thyroid cancer." (PMID 36120433, 2022). "Especially CD276, POSTN, and IFNA1 may be considered as new potential biomarkers associated with the prognosis of thyroid cancer." (PMID 36120433, 2022). "The study of POSTN regulation by p73 in thyroid cancer detected a strong upregulation of POSTN expression in a reporter assay in response to ΔNp73 overexpression, while we did not observe an upregulation of POSTN mRNA in response to ΔNp73 and only a mild effect in a reporter assay." (PMID 26930720, 2016). "A previous study has shown regulation of POSTN mRNA by p73 in a thyroid cancer cell line." (PMID 26930720, 2016). "However, the function of POSTN in thyroid cancer progression remains largely unknown." (PMID 38773979, 2024).
bone metastasis (7 papers, 2012 to 2025). Transfer of a neoplasm from its primary site to bones. "It was also shown that serum POSTN levels were significantly associated with the presence of bone metastasis." (PMID 29946533, 2018). "After subgroup analysis, a significant association between periostin expression and postoperative bone metastasis was observed." (PMID 23056395, 2012). "Therefore, future studies can validate whether periostin can be applied in liquid biopsy to predict the risk of bone metastasis occurrence in high-risk individuals." (PMID 38041134, 2023). "After survival analysis, periostin was shown to attain a significantly more distant postoperative bone metastasis and attained significantly poorer postoperative disease-specific survival." (PMID 23056395, 2012). "Additional studies are needed to clarify the specific role of POSTN in PC bone metastasis." (PMID 40841830, 2025). "POSTN, one of these genes, has been proposed as a serum biomarker for bone metastasis." (PMID 25485970, 2014). "Interestingly, patients with bone metastasis presented higher levels of POSTN compared to patients without bone metastasis and healthy controls." (PMID 29946533, 2018). "Furthermore, periostin was shown to attain a significantly more distant bone metastasis and worse disease-specific survival than those with none or low-expressed periostin protein (P = 0.001)." (PMID 23056395, 2012).